STAT1 (signal transducer and activator of transcription 1)
Diseases named in the same sentence as STAT1 in open-access papers (continued):
Sharing a sentence is not in itself a finding about the gene and the disease.
pancreatic cancer (71 papers, 2005 to 2026). "Steroid receptor coactivator‐1 (SRC‐1) reprograms tumor‐associated macrophages (TAMs) via signal transducer and activator of transcription 1(STAT1)‐mediated matrix metallopeptidase 12 (MMP12) transcription to drive perineural invasion (PNI) in pancreatic cancer." (PMID 40985319, 2025). "Ultimately, STAT1 transcriptionally activated PD-L1 and stability and exerted an immune associated function in pancreatic cancer, suggesting that PSMB8-AS1/miR-382–3p/STAT1/PD-L1 axis may act as a feasible therapeutic target for PC." (PMID 32891166, 2020). "Our findings revealed a novel mechanistic link between macrophage reprogramming and neural invasion, positioning the SRC‐1/STAT1/MMP12 axis as a promising therapeutic target for mitigating PNI in pancreatic cancer." (PMID 40985319, 2025). "For example, the overexpression of lncRNA PSMB8-AS1 has been found to enhance the growth, invasion, and metastasis of pancreatic cancer cells by modulating the miR-382-3p/STAT1/PD-L1 pathway." (PMID 40299524, 2025). "Although STAT1 has traditionally been considered a classic tumor suppressor, an increasing number of studies have shown that STAT1 has a pro-tumor effect in certain tumor contexts, including colorectal, ovarian, and pancreatic cancers." (PMID 40948762, 2025). "Recent investigations have illuminated the potential role of the IFN-γ/JAK/STAT1/IRF-1/procaspase-1 pathway as a pro-apoptotic mechanism in pancreatic cancer." (PMID 40909948, 2025). "Research has elucidated the regulatory role of the IFN-γ/JAK/STAT1 pathway in modulating MUC4 expression within pancreatic cancer cells." (PMID 40909948, 2025). "In summary, modulation of MUC4 expression via the IFN-γ/JAK/STAT1 pathway significantly promotes pancreatic cancer cell proliferation and metastasis." (PMID 40909948, 2025). "The PSMB8-AS1/miR-382-3p/STAT1/PD-L1 axis shows potential as a viable therapeutic target in pancreatic cancer." (PMID 38462628, 2024). "PSMB8-AS1 enhances the proliferation and metastasis of pancreatic cancer cells by acting as a sponge for miR-382-3p, leading to an upregulation of STAT1 expression." (PMID 38462628, 2024). "As an epithelial-mesenchymal transition (EMT) related lncRNA, researchers found that PMSB8.AS1 promoted pancreatic cancer (PC) progression via STAT1 by sponging miR-382-3p involving regulation PD-L1." (PMID 36739404, 2023). "For instance, the invasion and proliferation ability of pancreatic cancer is significantly inhibited by miR-382 by targeting STAT1/PD-L1." (PMID 36894950, 2023). "PSMB8-AS1 is involved in pancreatic cancer progression through modulating miR-382-3p/STAT1/PD-L1 axis." (PMID 36917093, 2023). "STAT1 was suggested as a prognostic biomarker in solid tumors and pancreatic cancer in previous studies." (PMID 36157222, 2022). "The lncRNA PSMB8-AS1 upregulates the expression of STAT1 by sponging miR-382-3p to increase the level of PD-L1, resulting in the promotion of proliferation, invasion, and migration in pancreatic cancer." (PMID 35266439, 2022). "The upregulation of PSMB8-AS1 can promote STAT1 expression and contribute to pancreatic cancer malignant behaviors by modulating the miR-382-3p/STAT1/PD-L1 axis." (PMID 35819532, 2022). "For example, PSMB8-AS1 contributes to pancreatic cancer progression by modulating the miR-382-3p/STAT1/PD-L1 axis." (PMID 33833992, 2021). "N4 also selectively inhibited STAT3 activation in pancreatic cancer cells, while displayed little impact on STAT1 and STAT5, which shared the most conserved structure features to STAT3 among STAT members." (PMID 33420372, 2021). "STAT1 is activated by interferon-γ (IFNγ) in pancreatic stellate cells (PSCs), which plays an important role in chronic pancreatitis and pancreatic cancer." (PMID 33505218, 2021).
pancreatic cancer (continued). "Signal Transducer and Activator of Transcription 1 (STAT1) is a transcription factor involved in the JAK-STAT signaling pathway and defined as a prognostic factor in pancreatic cancer, is inversely associated with metastasis and tumor differentiation." (PMID 32823814, 2020). "Next, we analyzed the correlation between STAT1 and PD-L1 expression in the TCGA database, we found that STAT1 was positively correlated with PD-L1 in the pancreatic cancer tissue." (PMID 32891166, 2020). "lncRNA PMSB8-AS1 promotes pancreatic cancer progression via STAT1 by sponging miR-382–3p involving regulation PD-L1." (PMID 32891166, 2020). "Fortunately, IFNγ can sensitize pancreatic cancer cells to gemcitabine via the STAT1/FOXM1/NFκB axis." (PMID 30782607, 2019). "Immunohistochemical analysis demonstrated a negative association of FOXM1 expression and the level of phosphorylated signal transducer and activator of transcription 1 (pSTAT1) in human pancreatic cancer tissues." (PMID 30782607, 2019). "Our results suggest that the STAT1/FOXM1/NFκB axis can inhibit chemotherapy resistance in pancreatic cancer." (PMID 30782607, 2019). "Taken together, these results indicated that the IFNγ/STAT1 pathway suppressed FOXM1 transcription directly in pancreatic cancer cells." (PMID 30782607, 2019). "Mechanistically, monensin suppresses numerous cancer-associated pathways, such as E2F/DP1, STAT1/2, NFkB, AP-1, Elk-1/SRF, and represses EGFR expression in pancreatic cancer lines." (PMID 30559409, 2018). "We previously demonstrated that the pro-inflammatory cytokines IFN-γ and LPS increased DUOX2 expression, with concomitant H2O2 production and DNA damage, in human pancreatic cancer cell lines by activating signal transduction through both Stat1 and NF-κB." (PMID 27637085, 2016). "Further, STAT1 protein is reported to be expressed in 88% of primary pancreatic cancer patients, which implies the clinical significance of STAT1 in pancreatic cancer." (PMID 25686822, 2015). "In this paper, we investigated the role of E2F1 and STAT1 transcription factors on MUC4 regulation in pancreatic cancer cells and found that both the transcription factors can positively regulate MUC4 transcription." (PMID 22537161, 2012). "The case study, presented here, investigates interferon-gamma (IFNγ) induced STAT1 signalling in two cell types that play a key role in pancreatic cancer development: pancreatic stellate and cancer cells." (PMID 23284277, 2012). "All human pancreatic cancer cells tested expressed various levels of Stat1, Stat3, and Stat6 proteins." (PMID 15714203, 2005). "In conclusion, this study elucidates the role of the IFN-γ/JAK/STAT1/CCL2/MMP13 pathway in exerting antitumor effects in pancreatic cancer by activating immune cells, which challenges the conventional understanding of CCL2 and MMP13 as promoters of tumor progression." (PMID 40909948, 2025). "Additionally, [pIC]PEI, which aids in cytoplasmic delivery of polyinosinic-polycytidylic acid and Nifurtimox, has promising therapeutic effects in pancreatic cancers by modulating immune cell response within the IFN-γ/STAT1 pathway." (PMID 40909948, 2025). "A previous study reported that surface expression of PD-L1 and phosphorylation of STAT1 in pancreatic cancer cell lines was elicited by treatment with conventional chemotherapeutic drugs including 5FU, gemcitabine, and paclitaxel, although the correlation with phenotypic drug response was not clear." (PMID 39461475, 2024). "Furthermore, STAT1 inhibits the expression of FOXM1 in pancreatic cancer cells, thereby promoting gemcitabine-induced apoptosis." (PMID 39551792, 2024). "Moreover, STAT1 expression and activation are abnormal in malignant pleural mesothelioma, pancreatic cancer, and breast cancer." (PMID 38191598, 2024). "Furthermore, evidence shows that lncRNA can upregulate STAT1 expression by binding to miRNA, elevating PD-L1 expression in pancreatic cancer." (PMID 38012210, 2023).
pancreatic cancer (continued). "STAT1 has been reported to be protective in gastric cancer, liver cancer, and melanoma, but hazardous in glioblastoma and sarcoma, and controversial in breast and pancreatic cancer." (PMID 37275859, 2023). "Additionally, abnormally expressed lncRNA PSMB8-AS1 is involved in the progression of pancreatic cancer by enhancing the STAT1/PD-L1 pathway." (PMID 35819532, 2022). "In addition, pancreatic cancer (PC) growth is aided by irregularly amplified lncRNA PSMB8-AS1 through the enhancement of the STAT1/PD-L1 network." (PMID 36497125, 2022). "It has been reported that the JAK2/STAT1 pathway may be involved in the regulation of PD-L1 expression in pancreatic cancer cells, which is increased by gemcitabine or paclitaxel." (PMID 34359638, 2021). "Zhang and Giulietti reported that lncRNA PSMB8-AS1 could contributed to pancreatic cancer progression via modulating miR-382-3p/STAT1/PD-L1 axis and might enable to serve as a prognostic biomarker for pancreatic cancer." (PMID 34281486, 2021). "Furthermore, STAT1 was found to be an inhibitor of Forkhead Box protein M1 (FoxM1) that acts as an oncogene via NF-κB signaling in pancreatic cancer." (PMID 32823814, 2020). "Therefore, blocking STAT1/FOXM1/NFkB axis by interferon γ (IFNγ) can increase the sensitivity of pancreatic cancer to gemcitabine." (PMID 30782607, 2019). "IFNγ could be used to down-regulate the expression of FOXM1 through STAT1 phosphorylation, thereby increasing the sensitivity of pancreatic cancer cells to gemcitabine." (PMID 30782607, 2019). "DUOX2 expression, unlike that of the DUOX1 homolog, is associated with progression of pancreatic cancer; the pro-inflammatory cytokine IFN-γ triggers Stat1-mediated DUOX2/DUOXA2 up-regulation in pancreatic cancer cell lines, contributing to increased intra- and extracellular ROS production." (PMID 28578276, 2017). "Furthermore, we integrated a fourth model, studying the enhancement of STAT1 in pancreatic cancer, published already on BioModels as an SBML model." (PMID 29244826, 2017). "Notably, silencing of EGFR family member in pancreatic cancer cells decreased MUC4 expression through reduced phospho-STAT1." (PMID 25686822, 2015). "Hence, these results imply that pan-EGFR inhibitor inhibits phospho-STAT1 mediated response to regulate MUC4 expression in pancreatic cancer cells, thereby abrogating tumor advancement towards metastasis." (PMID 25686822, 2015). "In addition to the transfection studies, treatment of pancreatic cancer cells with canertinib and afatinib at the indicated concentrations also resulted in significant inhibition of phospho-STAT1 and decrease of MUC4 mucin protein expression." (PMID 25686822, 2015). "Interestingly, our previous study has shown that the MUC4 promoter has STAT1 binding sites and serine phosphorylation of STAT1 (ser727) regulates MUC4 expression in pancreatic cancer cells." (PMID 25686822, 2015). "IFN-γ upregulates MUC4 in pancreatic cancer cells through STAT1 expression." (PMID 22479354, 2012). "Consequently, inhibition of interferon gene expression by the STAT1 inhibitor ruxolitinib has been demonstrated as a potential therapeutic approach in preclinical models of pancreatic cancer, with suggested utility in patients with a high interferon gene signature." (PMID 36429078, 2022). "In addition, PDL1 may be associated with various lncRNAs, and the lncRNA, PSMB8-AS1, promotes pancreatic cancer progression by regulating the miR-382-3p/STAT1/PDL1 axis." (PMID 35692827, 2022). "A study proposed that STAT1 could also enhance the sensitivity to gemcitabine in pancreatic cancer." (PMID 36157222, 2022). "Interestingly, erlotinib was unable to attenuate MUC4 protein level in pancreatic cancer cells which could be possibly due to the unaltered phosphorylation status of STAT1 (Ser 727)." (PMID 25686822, 2015). "At first, we examined whether pancreatic cancer cell lines express Stat1, Stat3, and Stat6." (PMID 15714203, 2005).
pancreatic cancer (continued). "In pancreatic cancer, a similar mechanism is observed, with PMSB8-AS1 sponging miR-382-3p, leading to increases in STAT1 and PD-L1 expression, and again enabling immune escape." (PMID 41154428, 2025). "Investigations into pancreatic cancer have revealed that both CCL2 and MMP13 are regulated by the upstream IFN-γ/STAT1 signaling, which facilitates macrophage polarization." (PMID 40909948, 2025). "The STAT1, STAT3, EGFR, and Notch‐1 signaling pathways can be blocked to prevent the development of pancreatic cancer." (PMID 38690008, 2024). "Curcumin has the ability to inhibit not only the protein phosphorylation of STAT1 and STAT3 but also the EGFR and Notch‐1 signaling processes, all of which play important roles in the progression of pancreatic cancer." (PMID 38690008, 2024). "In pancreatic cancer, DDX18 promotes immune escape through STAT1 activation, shielding cancer cells from immune surveillance." (PMID 38732173, 2024). "Curcumin also inhibits phosphorylation STAT-1, STAT-3, and Notch signaling pathways which are responsible for pancreatic cancer cell growth." (PMID 34483905, 2021). "Specifically, treatment of pancreatic cancer with doxorubicin, paclitaxel or 4-hydroxy-cyclophosphamide (4H-CPA) chemotherapies resulted in CAF-induced STAT-1 and NF-κB activity leading to the secretion of ELR motif-positive (ELR+) chemokines." (PMID 33276524, 2020). "For example, STAT-3 activation counteracts the effects of STAT-1 on p21 and p27 expression and activates a survival MAPK and AKT-dependent pathway which inhibits the occurrence of autophagy in pancreatic cancer cells." (PMID 31320837, 2019). "S-nitrosylated proteins in pancreatic cancer pathway identified in this study also include Rac1, Rac2, CDC42, STAT1, and RB, which are all important regulators of pancreatic cancer cells." (PMID 31801946, 2019). "To prove this we transiently inhibited endogenous EGFR using siRNA in pancreatic cancer cells and, as expected, transient knockdown of EGFR expression led to inhibition of phospho-STAT1 thereby down regulating MUC4 mucin protein expression." (PMID 25686822, 2015). "The expression levels of IFIT3 in pancreatic cancer cells were alterable as expected by IFN treatment, and by inhibition of STAT1 and NFκB signaling." (PMID 25650658, 2015). "We find a positive correlation between the binding of E2F1 and STAT1 with MUC4 promoter and its expression in pancreatic cancer cell lines." (PMID 22537161, 2012). "Our studies show that agents that can promote the growth and invasion of pancreatic cancer cells induce the MUC4 gene through multiple pathways and this induction requires the transcriptional activity of E2F1 and STAT1." (PMID 22537161, 2012). "As a coactivator of STAT1, SRC‐1 promotes MMP12 transcription, suggesting that SRC‐1 may be an attractive therapeutic target for PNI in pancreatic cancer." (PMID 40985319, 2025). "The analytic results demonstrated that 7 upregulated (MMP9, CXCL8, ACTB, ITGB1, STAT1, TOP2A and CDK1) and 2 downregulated (GNMT and ABAT) hub genes may act as the key genes in pancreatic cancer." (PMID 31061236, 2019). "For example, MMP9 participated in pancreatic cancer angiogenesis and invasion; CXCL8 promoted invasiveness and angiogenesis in pancreatic cancer; ITGB1 was upregulated in pancreatic cancer and increased ITGB1 indicated a poor outcome; and STAT1 enhanced pancreatic cancer growth and metastasis." (PMID 31061236, 2019). "Given that nicotine stimulates the binding of E2F1 to a variety of promoters, and since STAT1 is known to induce MUC4, we decided to examine whether these factors mediate the induction of MUC4 in pancreatic cancer cells." (PMID 22537161, 2012). "In this study, we found that PSMB8-AS1 and STAT1 are existing binding sites of miR-382–3p, and demonstrated that PSMB8-AS1 promotes the expression of STAT1/PD-L1, forming a new theoretical basis for pancreatic cancer progression and providing a possible approach for targeted therapy." (PMID 32891166, 2020).
pancreatic cancer (continued). "Western blot analysis confirmed that the protein level of phospho STAT1, total STAT1 and MUC4 protein is not altered upon erlotinib treatment in CD18/HPAF pancreatic cancer cells for 24h." (PMID 25686822, 2015).
Autoimmunity (63 papers, 2010 to 2025). The occurrence of an immune reaction against the organism's own cells or tissues. "Compared with both other DBD mutations and mutations elsewhere in STAT1, T385M conferred significantly higher rates of infection, bronchiectasis, autoimmunity, and premature death (p < 0.001)." (PMID 41394881, 2025). "The immunological background for the increased autoimmunity in STAT1 GOF is not fully understood but is believed to be caused by increased responses to type I IFN signaling." (PMID 40881691, 2025). "Here, we generated a mouse model to identify potential cellular, molecular and environmental mechanisms linked to autoimmunity in STAT1 GOF patients with the DBD T385M mutation." (PMID 37275873, 2023). "On the other hand, the STAT1 GOF-associated autoimmunity, affecting over one third of patients, is largely unexplained." (PMID 37358695, 2023). "Preliminary in vitro studies on the potential therapeutic use of JAK inhibitors are already being conducted in patients with autoimmunity or autoinflammation symptoms associated with STAT1 overactivation." (PMID 37140667, 2023). "Given the increased infection susceptibility and risk of autoimmunity, STAT1 GOF treatment is challenging and can include antimicrobial and immunosuppressive therapy." (PMID 37622085, 2023). "JAK inhibition (with compounds ruxolitinib or baricitinib) have recently proved effective in ameliorating both the candida susceptibility and the autoimmunity in some patients with STAT1 GOF mutations." (PMID 36172362, 2022). "Monocytes have been associated with autoimmunity and autoimmune phenomena represent frequent complications in patients with STAT1 GOF mutations." (PMID 36172362, 2022). "Taken together, we show that monocytes likely play an active role in both the microbial susceptibility and autoimmunity in STAT1 GOF CMC." (PMID 36172362, 2022). "Heterozygous STAT1 mutations that confer hyper-responsiveness to stimulation are associated with a mixed phenotype characterized by infection, autoimmunity, and inflammation." (PMID 34603291, 2021). "In preclinical research, ruxolitinib has been reported to reverse dysregulated T helper cell responses and control autoimmunity resulting from signal transducer and activator of transcription 1 (STAT1) gain-of-function mutations." (PMID 34276662, 2021). "Patients with dominant GOF mutations in STAT1 present with chronic mucocutaneous candidiasis and lower respiratory tract infections with a subset of patients developing severe organ-specific autoimmunity including T1D (4% of patients)." (PMID 30888520, 2019). "STAT1 is an essential part of interferon signaling, and STAT1-deficiency results in heightened susceptibility to infections or autoimmunity in both mice and humans." (PMID 21949815, 2011). "We recently showed that individuals with DBD mutations had a higher prevalence of autoimmunity compared with other STAT1 GOF patients, including endocrinopathies, autoimmune gastrointestinal disease (enteropathy or hepatitis), autoimmune cytopenia’s and interstitial lung disease." (PMID 37275873, 2023). "Amongst the functional aberrations, a selectively enhanced responsiveness to TLR7/8 stimulation, but not to other TLR ligands, was noted, which might represent a contributing mechanism in the pathogenesis of STAT1 GOF-associated autoimmunity." (PMID 36172362, 2022). "In addition, new therapies such as ruxolitinib and baritinib have been reported for CMC or steroid-dependent severe autoimmunity caused by STAT1 GOF." (PMID 33777053, 2021). "The increased risk of autoimmunity in these patients might be explained by an enhanced transcription of IFN-induced genes due to signal-induced increased levels of phosphorylated STAT1." (PMID 34603291, 2021).